ZFP69B (ZFP69 zinc finger protein B)
Description:
May be involved in transcriptional regulation. Essential for Golgi structural integrity.
Synonyms: ZNF643; ZKSCAN23B; FLJ34293; ZSCAN54B
Tractability: PROTAC: UniProt records ubiquitination sites on it.
Gene: Protein-coding gene on chromosome 1 (40,450,053 to 40,464,142, forward strand). Ensembl gene ENSG00000187801.
Subcellular location: Nucleus
Subcellular location (Human Protein Atlas): Nucleoplasm; Cytosol
Pathways (Reactome):
Gene expression (Transcription): Generic Transcription Pathway
Gene Ontology:
Molecular function: protein binding; DNA-binding transcription factor activity, RNA polymerase II-specific; RNA polymerase II transcription regulatory region sequence-specific DNA binding
Biological process: Golgi organization; regulation of transcription by RNA polymerase II; regulation of DNA-templated transcription
Cellular component: nucleolus; nucleus
Genetic constraint (gnomAD): Loss-of-function variants: 16 observed, 17.8 expected, observed/expected ratio (o/e) 0.9, 90% interval 0.61 to 1.37. The upper end of that interval is the gene's LOEUF score, 1.37, which puts it in group 5 of 6, group 1 being the genes least tolerant of losing a copy. Missense variants: 581 observed, 645.71 expected, observed/expected ratio (o/e) 0.9, 90% interval 0.84 to 0.96. Synonymous variants: 218 observed, 224.45 expected, observed/expected ratio (o/e) 0.97, 90% interval 0.87 to 1.09.
Homologues: Orthologues: chimpanzee ZFP69B (99% identical), macaque ZFP69B (96% identical), dog ZFP69B (87% identical), pig ZFP69B (83% identical), Drosophila melanogaster CG3281 (24% identical), Drosophila melanogaster CG2712 (22% identical), Drosophila melanogaster Phs (21% identical). Paralogues in human: ZFP69 (69% identical), ZNF805 (38% identical), ZNF619 (37% identical), ZFP37 (37% identical), ZFP90 (37% identical), ZNF264 (36% identical), ZNF266 (36% identical), ZNF554 (36% identical), ZNF582 (36% identical), ZNF614 (36% identical), ZNF25 (35% identical), ZNF599 (35% identical), and 50 more.
Diseases named in the same sentence as ZFP69B in open-access papers:
ZFP69B is named in the same sentence as 8 diseases in open-access papers, as found by Europe PMC text mining. Sharing a sentence is not in itself a finding about the gene and the disease. The quoted sentences say what the papers report.
gastric cancer (3 papers, 2020 to 2022). A primary or metastatic malignant neoplasm involving the stomach. "ZFP69B has been reported to predict the prognosis of gastric cancer." (PMID 36249031, 2022). "The functions of ZNF823, ZFP69B, SP6, KYNU, KIF21B, and TTF2 have not been reported in gastric cancer." (PMID 32848739, 2020).
breast carcinoma (2 papers, 2019 to 2022). "In addition, computational prediction indicated that DPP4 was down-regulated in breast cancer, TF was down-regulated in other tumors and ZFP69B was up-regulated in other tumors." (PMID 36568247, 2022). "In addition, the possible ferroptosis mechanisms of CDKN2A, PSAT1, SLC7A11, LAMP2, CAV1, and HMGB1 in TNBC and ASNS, ZFP69B, ELAVL1, TF, HELLS, and DPP4 in breast cancer have not been reported." (PMID 36568247, 2022).
tumor (2 papers, 2019 to 2023). "We previously detected the ZNF643/ZFP69B gene upregulated in multiple tumors, and we speculated it may play a role in tumor biology." (PMID 38003570, 2023).
ZFP69B also shares sentences with these, for which no sentence is quoted: cancer (3 papers); lung carcinoma (2); diabetes (1); ovarian carcinoma (1); triple-negative breast carcinoma (1).